MMP9 (matrix metallopeptidase 9)
Diseases named in the same sentence as MMP9 in open-access papers (continued):
Sharing a sentence is not in itself a finding about the gene and the disease.
breast carcinoma (continued). "In summary, inhibition of Src kinase suppressed TNBC tumor growth and metastasis, and Src inhibitors such as BJ-2302 may constitute a novel therapeutic tool to treat breast cancer that expresses high levels of CTSS and MMP-9." (PMID 30185799, 2018). "Overexpression of MMP-9 is a clear feature of triple-negative and HER2-positive breast cancers." (PMID 30262739, 2018). "Although both MMP-9 and CD163 have been traditionally related with M2-phenotype, here we show that they do not always correlate with worse prognosis, as previously reported in breast cancer." (PMID 30558648, 2018). "We found that NLRP1 transfection promoted breast cancer cell line MCF-7 proliferation, migration, and invasion by possibly activating EMT and inflammasomes, mesenchymal markers vimentin, C-myc, MMP-9, and snail were upregulated, and then epithelial marker E-cadherin was downregulated." (PMID 29214170, 2017). "In addition to SNAIL1 effects, LOXL2 influences expression of SPARC and the extracellular proteins TIMP1 and MMP9; in fact, LOXL2 was noted as prognostic factor in breast cancer." (PMID 28425924, 2017). "In the breast TME, fibroblasts and breast carcinoma cells may produce TGF-β cytokines and MMP9 thereby contributing to tumor vascularization." (PMID 28423685, 2017). "Low-risk breast cancers showed significantly lower matrix metalloproteinase (MMP)-2 expression (P = 0.000), lower MMP-9 expression (P = 0.001), and lower microvessel density (MVD) values (P = 0.008) compared with non-low-risk breast cancers." (PMID 29371992, 2017). "Our study corroborates with other studies, which have shown that 20-HETE inhibition reduces invasion in vitro, and angiogenesis and metastasis in vivo by decreasing VEGF and MMP-9 expression in human non-small cell lung cancer and MDA-MB-231 breast cancer mouse models." (PMID 28609459, 2017). "Here we show that pre-treatment with an inhibitor of the Src-family kinases (PP2) blocked the increase in cell migration and invasion in colon and breast cancer cells and that CAV1 silencing decreased particularly MMP9 activity induced by the anti-neoplastic drugs." (PMID 29340103, 2017). "Collectively, we conclude that TOPK functions as a key mediator of LPS/TLR4-induced breast cancer cell migration and invasion through regulation of MMP9 expression or activity, implying a potential role of TOPK as a therapeutic target linking LPS-induced inflammation to breast cancer development." (PMID 28212583, 2017). "Furthermore, analyzing by Real-time PCR 58 breast cancer samples from our SGBH patient cohort, we found a significant correlation between Morgana and MMP9 expression levels." (PMID 29158506, 2017). "Zymography assays with 48- and 96-hr conditioned media revealed that breast cancer cells alone secrete a 92kDa zymogen form of MMP9 (pro-MMP9), whereas fibroblasts do not produce MMP9 but secrete significant amounts of MMP2/gelatinase-A." (PMID 28423685, 2017). "Furthermore, it has been demonstrated in MDA-MB-231 cells, that TNF-α increased MMP-9 expression and activity by inducing AP-1 DNA binding activity, thus reinforcing the concept of a protumorigenic effect of TNF-α in breast cancer." (PMID 29202842, 2017). "In conclusion, our study demonstrates that TOPK is a key mediator in LPS/TLR4 signaling to trigger breast cancer invasion, and that LPS/TLR4 signaling enhances expression and activity of TOPK leading to NF-κB activation, thereby enhancing MMP9 expression and subsequent breast cancer cell invasion." (PMID 28212583, 2017). "To further elucidate the molecular mechanism through which GDF15 enhances breast cancer cell invasion, we measured expression levels of matrix metalloproteinases (MMP) MMP2 and MMP9, which are transcriptional targets of FoxM1 and mediators of cancer cell invasion." (PMID 29212236, 2017). "However, curcumin at certain doses and times can inhibit TGF-β1 activity in regulating MMP-9 and activation of SMAD-2, ERK1/2, and p38 in breast cancer cells." (PMID 29445400, 2017).
breast carcinoma (continued). "We also hypothesized that LPS-mediated TOPK expression or activity leads to secretion of MMP9 thereby degrading ECM, which then activated TLR4 and enhanced breast cancer cells invasiveness." (PMID 28212583, 2017). "In addition, epithelial–mesenchymal transition (EMT)-related genes SLUG, MMP9, ZEB1 and SNAIL were also elevated, while E-cadherin, an epithelial cell marker, were reciprocally decreased in all three breast cancer cell lines examined." (PMID 28703802, 2017). "Since MMP-9 shows very strong correlation with CK19 mRNA in breast carcinoma of no special type metastases, expression of MMP-9 in sentinel lymph nodes should be considered as useful method whenever OSNA analysis is not available." (PMID 27110764, 2016). "Interestingly, after knocking down of the uPA in the breast carcinoma MDA-MB-231 by siRNA, in vitro migration of the cells was effectively decreased along with a significant reduction in the extracellular MMP9 activities." (PMID 26906973, 2016). "Accordingly, treatment with low-dose (10–20 μg/mL) EtOAc extracts for 24 h decreased cell migration by downregulating protein expression of MMP2, MMP9, cyclin B, vimentin, and snail protein in MDA-MB-231 cells, indicating decreased breast cancer cell growth both in vivo and in vitro." (PMID 27078842, 2016). "Previously, the MMP-9 showed a strong immunostaining in deceased breast cancer patients with metastasis, whereas there was no marker in normal breast tissues." (PMID 27110764, 2016). "Due to the fact that Asp-UA could decrease the expression of CAMs, we further assessed the expression of crucial proteins including MMP-2, MMP-9 and COX-2, which are critical functional molecules within the tumor invasion process in breast cancer cells." (PMID 27683033, 2016). "Consequently, UDP-induced breast cancer cell invasion was significantly inhibited by both MRS2578 and the MMP-9 inhibitor." (PMID 27074554, 2016). "We found that a TNF-α-induced enhancement of breast cancer cell migration was accompanied by an increased secretion of MMP9, but not MMP2, into the culture media." (PMID 27042827, 2016). "Moreover, MMP13 can activate MMP9 and TGFβ to increase the local expression of RANKL at the tumor-bone interface in breast cancer." (PMID 26863138, 2016). "Our findings were not only consistent with previous studies on several known breast cancer-related lncRNAs and mRNAs, such as HOTAIR7, BRCA232, MMP9 and MMP1133, but more importantly, our study was able to identify novel breast cancer-related lncRNAs and lncRNA-mRNA co-expression networks." (PMID 27597120, 2016). "Moreover, linear regression analyses showed that higher Gpr132 expression was significantly correlated with higher expression of pro-inflammatory markers including CCL2 (MCP-1), MMP9 and PTGS2 (COX-2) in breast cancer lesions." (PMID 27692066, 2016). "Moreover, previous studies have identified that β-catenin, a transcription factor, involves in breast cancer metastasis via induction of MMP2, MMP-9, and UPA genes." (PMID 25658913, 2015). "Others have previously reported that in both breast tumors and cell lines, there is a negative association between the expression of MMP-9 and one of its natural inhibitors, RECK, a key breast cancer metastasis suppressor gene." (PMID 25668816, 2015). "MMP-2, MMP-9 and eukaryotic transcription factor-1(ETS-1) co-expression might be used as a poor prognostic factor in breast cancer patients." (PMID 26674531, 2015). "Both TSP50 and MMP9 are aberrantly expressed in human breast cancer tissues, and here we found TSP50 overexpression promoted MMP9 expression through NF-κB signaling pathway, therefore, we examined the correlation of TSP50 with p65 and MMP9 in human breast cancer clinical samples." (PMID 25811800, 2015).
breast carcinoma (continued). "It is demonstrated that the Ahr-active omeprazole decreases invasion and metastasis in estrogen receptor (ER)-negative breast cancer cell lines by down-regulation of matrix metalloproteinase-9 (MMP-9) and C-X-C chemokine receptor 4 (CXCR4)." (PMID 26377202, 2015). "But in our study, TIMP-1 expression was not seemed to be the regulator of MMP-9 activation in breast cancer cells." (PMID 25888829, 2015). "In this study, we determined whether BRACs inhibited breast cancer cell invasion by suppressing RAS/RAF/MAPK signaling, and the possible involvement of MMP2 and MMP9, which are regulated by JNK, was involved in the antimetastatic activity of BRACs." (PMID 26649302, 2015). "Our study presents several important findings: (i) Increased expression and activity of MMP-2 and MMP-9 among others in metastatic breast cancer cell lines, xenografts, and lungs as compared with non-metastatic lines." (PMID 28721370, 2015). "A separate clinical study of fifty breast cancer patients and 34 healthy controls showed higher levels of gelatinase-A (MMP-2) and gelatinase-B (MMP-9) in sentinel lymph nodes containing macroscopic metastatic nodules with respect to lymph nodes that were free of cancer cells." (PMID 25950608, 2015). "Most importantly, we found that PYK2 depletion markedly reduced EGF/HRG-induced MMP9 transcription and its subsequent gelatinase activity in SKBR3 cells, as determined by zymography assay, implying that PYK2 plays an important role in breast cancer metastasis." (PMID 26084289, 2015). "Besides, it had been demonstrated that Fra-1 directly induced MMP-1 and MMP-9 promoter activities in breast cancer cells and stimulated MMP-2 and MMP-9 expression to enhance the motility and invasion of lung cancer cells." (PMID 26337460, 2015). "Thus, breast cancer cells can secrete CCL2, CCL5, or osteopontin which promotes the expression of cathepsin K and matrix metalloproteinase 9 (MMP9), thus enhancing OC functions." (PMID 26064994, 2015). "Previous researches also showed that the downstream factors of ErbB pathway, such as MMP-9, uPA, EMMPRIN, and PAI-1, could be induced by AREG in head and neck cancer, breast cancer, and malignant mesothelioma cell lines." (PMID 25762634, 2015). "Therefore TAM and 3BP the ability to modulate MMP-2/MMP-9 activity and VEGF levels in human breast cancer in vitro." (PMID 26526196, 2015). "Moreover, BRACs treatment inhibited the HER2/MAPK/MMP9 signaling pathway, leading to the suppression of metastasis in HER2+ breast cancer cells." (PMID 26649302, 2015). "Our results indicate that glaucine is a potent inhibitor of PMA-induced MMP-9 expression in two breast cancer cell lines (MCF-7 and MDA-MB-231), suggesting that the ability of glaucine to inhibit MMP-9 expression may be a general phenomenon." (PMID 25670016, 2015). "Similarly, in human breast cancer, RUNX2 directly regulates the expression of MMP9 and MMP13, bone sialoprotein and OPN, IL-8 and the TGFβ-induced PTHrP levels and mediates invasion of the human breast cancer cell lines MDA-MB-231 and MCF7." (PMID 26204939, 2015). "Ectopically expressed LKB1 is also reported to reduce MMP-9 mRNA and protein expression, and to inhibit invasion of breast cancer cells, but the molecular mechanisms involved have not been explored." (PMID 25384047, 2014). "When the expression of MMP-9 in breast cancer cell lines is considered, it is worth mentioning that cell lines with a basal-like phenotype and those that overexpressed HER2 reached the highest levels of MMP-9 expression." (PMID 25151367, 2014). "Taken together, these results indicate that the E2F1-mediated expression of MMP2, MMP9, MMP14, and MMP15 might be repressed by KDM2A, eventually hindering the migration and invasion of breast cancer cells." (PMID 25029110, 2014).
breast carcinoma (continued). "NDRG2 also suppresses matrix metalloproteinase-9 (MMP-9) expression through the induction of BMP-4 secretion and inhibits NF-kappaB activity and MMP-2 and -9 secretion, which abrogates the metastatic potential of breast cancer and fibrosarcoma cells." (PMID 25061501, 2014). "Gelatinase B/MMP-9 regulates mesenchymal migration, co-localises with integrins at lamellipodia on migrating cells and co-operates with αVβ3 integrin to increase breast cancer cell migration and metastatic capacity." (PMID 24473089, 2014). "Interestingly, many luminal breast cancer cell lines known to have HER2 gene amplification (AU565, UAA-893 and HCC2218) also exhibited high levels of MMP-9 expression." (PMID 25151367, 2014). "Moreover, our study indicated that, after TLR4 stimulation, breast cancer cells produced higher amounts of MMP-2, MMP-9 and VEGF, and as stimulus concentration increased within a certain range, the production of MMP-2, MMP-9 and VEGF also increased." (PMID 25299052, 2014). "To understand how overexpression of UEV1A leads to tumorigenesis and particularly metastasis in breast cancer cells, we surveyed NF-κB and metastasis-related genes and focused on two candidate genes, MMP1 and MMP9, both of which are highly induced upon UEV1A overexpression." (PMID 25022892, 2014). "Regarding breast cancer molecular subtypes, in the current research, triple negative breast cancers had the highest rate of fascin and MMP-9 expression." (PMID 24993803, 2014). "The aim of our study was to evaluate the serum levels of human epidermal growth factor receptor-2 (HER2), matrix metalloproteinase-9 (MMP-9), nitric oxide (NO), and total antioxidant capacity (TAC) in breast cancer patients and to correlate these markers with clinico-pathological parameters." (PMID 24634847, 2014). "Furthermore, our results indicate that not only MMP-9 is differentially expressed between each molecular subset but also, more importantly MMP-9 overexpression revealed itself as a startling feature of triple-negative and HER2-positive breast cancers." (PMID 25151367, 2014). "Metastatic colonization was enhanced in MMP9-knockout mice implanted with MMP9-expressing bone marrow, and MMP9 also promotes lung metastasis in the MMTV-PyVT multistage mammary tumor model, potentially deriving from the pro-angiogenic contribution of neutrophil MMP9 in the lungs." (PMID 24811362, 2014). "4–5 weeks post-tumor cell implantation, thioglycollate elicited macrophages from DA-3 scramble shRNA control or DA-3 SEMA7A shRNA mammary tumor-bearing mice were analyzed for the production of pro-angiogenic chemokines CXCL2/MIP-2, CXCL1 and matrix metalloprotease MMP-9." (PMID 24550834, 2014). "Our data have demonstrated that RABEX-5 can promote the migration and invasion of breast cancer cells; however, it is unknown whether RABEX-5 can modulate MMP-9 expression." (PMID 23941575, 2013). "Moreover, baicalin suppressed cell migration and invasiveness in breast cancer MDA-MB-231 cells by down-regulating p38 MAPK pathway and consequently MMP-2 and MMP-9 expression." (PMID 24167634, 2013). "Concentrations of both Matrix metalloproteinase-9 (MMP-9) and the naturally occurring Matrix metalloproteinase (MMP) inhibitor, Tissue inhibitor of metalloproteinases-1 (TIMP-1), have been investigated as tumor biomarkers in breast cancer." (PMID 24330623, 2013). "In breast cancer cells, miR-340 suppressed tumor cell migration and invasion by lowering the abundance of c-Met, a factor that promotes expression of MMP-2 and MMP-9; MMP-2 was additionally repressed by miR-29b in HCC cells, attenuating HCC cell invasiveness and angiogenic activity." (PMID 23325049, 2013). "In addition, Smad3 has been shown to be an important contributor to breast cancer cell invasion by controlling the expression of MMP-2 and MMP-9, two metalloproteinases involved in matrix degradation and invadopodia functions." (PMID 23405166, 2013).
breast carcinoma (continued). "However, there is one report showing that breast cancer cells stimulated production of inducible nitric oxide synthase and nitric oxide in RAW 264.7 macrophages, which in turn induced MMP9 and VEGF-A gene expression in breast cancer cells." (PMID 23349788, 2013). "Moreover, MMP9, a key member of the MMP family, plays a crucial role in the degradation of ECM and is upregulated in breast cancer as part of the extracellular matrix remodeling signature of this disease." (PMID 24236052, 2013). "The application of anti-MMP-9 DNAzyme (AM9D) for the treatment of primary and metastatic breast cancer was evaluated in vitro and in vivo using MDA-MB-231 cells and the MMTV-PyMT transgenic breast cancer mouse model." (PMID 23407024, 2013). "Interestingly, it has recently been demonstrated that WNT‐5A induced MMP9 mRNA expression through a ERK1/2 signaling mechanism in microglia, which appears contrary to our present findings on breast cancer cells." (PMID 23727359, 2013). "In particular, MMP-9/NGAL enzymatic activity was observed in the urine of breast cancer patients but not in healthy controls, and in 50% of urine samples from prostate cancer patients and in 49% of the urine from bladder cancer patients." (PMID 23760084, 2013). "In this study we evaluated genetic variation in MMP1, MMP2, MMP3, and MMP9 using data from a large collaborative case-control study of breast cancer in Hispanic and non-Hispanic white women (NHW) from the United States and Mexico." (PMID 23696797, 2013). "Although there was no dramatic increase in MMP-9 transcription, it is probable that the increased secretion was a result of post-transcriptional modification, as shown in breast cancer." (PMID 23914254, 2013). "Further, there was no relation between MMP-9:TIMP-1 and outcome when combining the parameters in a multivariate analysis, suggesting that the MMP-9:TIMP-1 complex has no value as a stand-alone prognostic marker in breast cancer." (PMID 24330623, 2013). "We also demonstrate that in vivo treatment with chitin microparticles, a substrate for CHI3L1, resulted in decreased production of CHI3L1, CCL2, CXCL2, and MMP-9 in BALF, and more specifically by interstitial and alveolar macrophages of mammary tumor-bearing mice." (PMID 24399973, 2013). "However, we did detect decreases in proangiogenic factors such as MCSF-1 and MMP-9 in the shEGFR-MDA-231 cells, as well as a panel of breast cancer cell lines treated with an EGFR tyrosine kinase inhibitor or PAR-34." (PMID 22276166, 2012). "In this in vitro study, the NM significantly inhibited breast cancer cell lines MDA-MB-231 and MCF-7 and uterine cell line SK-UT-1 secretion of u-PA and MMP-9 and increased their secretion of TIMP-2, suggesting its potential in modulating breast and uterine cancer invasion and metastasis." (PMID 22736175, 2012). "A previous in vivo study of the effects of NM on breast cancer supports these results in that it demonstrated significant inhibition of MDA-MB-231 xenograft tumor growth in nude mice and inhibition of MMP-9 and VEGF secretion and mitosis in the tissue of nutrient-supplemented mice." (PMID 22736175, 2012). "shEGFR-MDA-231 cells also produced decreased levels of the proangiogenic molecules macrophage colony stimulating factor-1 (MCSF-1) and matrix metalloproteinase 9 (MMP9), both of which were decreased by EGFR inhibitors in a panel of EGFR-positive breast cancer cells." (PMID 22276166, 2012). "Results in two breast cancer cells by Western blot ananlysis indicated that, ER alpha was recovered positive in ER-negative human breast cancer cell lines MDA-MB-231, and protein levels of MMP-9 and CyclinD1 were down-regulation (P < 0.05)." (PMID 21595884, 2011). "Breast tumor cells and ES cells secrete cytokines and chemokines to their microenvironment, however, breast cancer cells secrete a significantly higher level of soluble factors, which is correlated with tumor metastasis (e.g., M-CSF, OSM, MIP-2/CXCL-2, MMP-9, TIMP-1)." (PMID 22174624, 2011).